CUEDC2 (CUE domain containing 2)
Diseases named in the same sentence as CUEDC2 in open-access papers (continued):
Sharing a sentence is not in itself a finding about the gene and the disease.
lung carcinoma (1 paper, 2015). "Furthermore, Lung cancer cell lines expressed significantly lower levels of CUEDC2 compared to that in the 16HBE cells at both the protein and mRNA levels." (PMID 26023733, 2015). "Taken together, our results suggested that the phosphoinositol 3-kinase (PI3K)-Akt-p21-cyclin D1 signaling pathway might contribute to the CUEDC2-induced G0/G1-to-S phase cell cycle arrest in lung cancer cells." (PMID 26023733, 2015). "Furthermore, the expression level of CUEDC2 positively correlated with OS of lung cancer patients." (PMID 26023733, 2015). "Stable transfectants derived from two different lung cancer cell lines, A549-CUEDC2 and PC9- CUEDC2, expressed higher levels of CUEDC2 protein compared with the corresponding control cell lines and these two clones were used in subsequent experiments." (PMID 26023733, 2015).
ovarian carcinoma (1 paper, 2022). A malignant neoplasm originating from the surface ovarian epithelium. "Also, p38 MAPK pathway underlies the promotion of CUEDC2 in cisplatin resistance of ovarian cancer cells." (PMID 35739532, 2022).
triple-negative breast carcinoma (1 paper, 2022). An invasive breast carcinoma which is negative for expression of estrogen receptor (ER), progesterone receptor (PR), and human epidermal growth factor receptor 2 (HER2). "Here, we aimed to explore the contribution of CUEDC2, a novel CUE-domain-containing protein, to the activation of Wnt signaling and the tumorigenesis of triple-negative breast cancer (TNBC) and to determine the underlying mechanisms." (PMID 36231027, 2022).
virus infection (1 paper, 2023). "To determine whether the lnc-AROD–miR-324-5p axis involves CUEDC2 during IAV replication, we examined CUEDC2 expression after virus infection." (PMID 37036350, 2023).
tumor (9 papers, 2015 to 2023). "Our data supported CUEDC2 as a tumour suppressor because we found that overexpression of CUEDC2 inhibited AML cell proliferation, caused G1 arrest and prolonged the latencies of AML mouse in vitro and in vivo." (PMID 29991678, 2018). "Elevated IL‐4 and miR‐324‐5p levels in tumour microenvironment caused a decreased expression level of CUEDC2 in tumour‐associated macrophages, which resulted in excessive levels of proinflammatory cytokines, such as TNF‐α and IL‐6, and linked with both colitis and colon carcinogenesis." (PMID 37138536, 2023). "Previous studies showed that CUEDC2 deregulation may contribute to tumour initiation by causing chromosomal instability." (PMID 29991678, 2018). "A recent study suggested that CUEDC2 inactivates the spindle checkpoint, resulting in chromosome missegregation and aneuploidy, which caused neoplasia and preceded the inactivation of tumor suppressor genes at the early stages of tumor formation." (PMID 26023733, 2015). "As CUEDC2 binds to β-catenin and stabilizes it in tumor cells, we further explore the impact of CUEDC2 on the sub-cellular locations of β-catenin in control and CUEDC2 knockdown cells." (PMID 36231027, 2022). "CUEDC2 promotes TNBC tumor growth by enhancing Wnt signaling through directly binding to β-catenin and accelerating its nuclear translocation." (PMID 36231027, 2022). "The results showed that TNBC patients with higher expression of CUEDC2 in tumor tissues had a lower DFS probability (p = 0.0071)." (PMID 36231027, 2022). "We then determined if the knockdown of CUEDC2 in tumor cells prevents cell proliferation through modulating the Wnt/β-catenin signaling pathway." (PMID 36231027, 2022). "CUEDC2 knockdown significantly inhibited tumor cell proliferation in vitro and strongly reduced tumor formation in in vivo." (PMID 36231027, 2022). "The results showed that inhibiting CUEDC2 expression in tumor cells resulted in the remarkable suppression of tumor growth in vivo without obviously affecting the mice’s body weight, emphasizing the role of CUEDC2 in modulating TNBC tumor formation in vivo." (PMID 36231027, 2022). "Further studies have revealed that CUEDC2 suppresses tumor progression in lung adenocarcinoma, glioma, acute myeloid leukemia, etc.." (PMID 36231027, 2022). "The clinical data, based on 168 TNBC cases, showed that patients with lower expression of CUEDC2 in tumor tissues had a much longer DFS after surgery." (PMID 36231027, 2022). "CUEDC2 regulates the phosphorylation of STAT3 by regulating the stabilization of the SOCS1 or SOCS3 protein in tumor cells." (PMID 32393737, 2020). "In lung cancer, CUEDC2 also plays a tumor-suppressive role by inactivating the PI3K-Akt singling pathway." (PMID 33099540, 2020). "Similar to CUEDC1, another CUE domain-containing protein, CUEDC2, also appears to have a dual function, either as a tumor promoter or tumor suppressor." (PMID 33099540, 2020). "CUEDC2 expression was correlated with tumor T classification (P = 0.001) at clinical stage (P = 0.001) and tumor size (P = 0.033)." (PMID 26023733, 2015). "Ectopic expression of CUEDC2 decreased cell proliferation in vitro and inhibited tumor growth in nude mice in vivo." (PMID 26023733, 2015). "Indeed, peptides targeting the binding sites of CUEDC2 and β-catenin reduced the malignant phenotype of TNBC in vitro and caused the remarkable inhibition of tumor growth in vivo." (PMID 36231027, 2022). "Furthermore, knockdown of β-catenin phenocopied the actions of CUEDC2 knockdown in TNBC cells, which further validated the essential role of β-catenin in mediating the effects of CUEDC2 in accelerating the malignant behaviors of tumor cells." (PMID 36231027, 2022). "We next identified the molecular mechanism by which CUEDC2 accelerated TNBC tumor cell growth." (PMID 36231027, 2022). "Finally, we explored downstream targets of CUEDC2 essential for BCYRN1-mediated tumor suppressor function." (PMID 32978519, 2020).
tumor (continued). "Interestingly, CUE domain-containing protein 2 (CUEDC2) is a multi-functional protein in cancer and possesses both oncogenic and tumor-suppressive properties." (PMID 33099540, 2020). "Although roles of CUEDC2 in the tumorigenesis of many cancers were studied, controversy remains regarding whether CUEDC2 functions as a tumour suppressor gene or oncogene." (PMID 29991678, 2018). "Knockdown of endogenous CUEDC2 by short hairpin RNAs (shRNAs) increased tumor growth." (PMID 26023733, 2015). "However, in the β-catenin knockdown TNBC cells, the effects of siRNA CUEDC2 on cell proliferation, migration, and invasion were diminished, confirming that β-catenin is responsible for CUEDC2′s regulation of the tumor cell action." (PMID 36231027, 2022). "Further, we inoculated the control and CUEDC2-knockdown TNBC cells into the mammary fatty pads of NPG mice and explored the role of CUEDC2 in TNBC tumor formation in vivo." (PMID 36231027, 2022). "Although S3I-201, a STAT3 inhibitor, inhibited cell proliferation, CUEDC2 knockdown did not reduce cell proliferation in S3I-201 treated tumor cells, confirming that CUEDC2 inhibits tumor cell growth through a STAT3-independent manner." (PMID 36231027, 2022). "Knockdown of CUEDC2 suppressed cell proliferation, clonal formation, migration, and invasion abilities in MDA-MB-231 and MDA-MB-468 cells, highlighting that CUEDC2 promotes TNBC tumor cell growth and invasion in vitro." (PMID 36231027, 2022). "Next, we examined whether disrupting the interactions of CUEDC2 and β-catenin was a promising approach to restrain TNBC tumor formation." (PMID 36231027, 2022). "The overexpression or constitutive activation of STAT3 promotes tumor cell proliferation, which is independent of CUEDC2." (PMID 36231027, 2022). "However, CUEDC2 knockdown failed to reduce cell proliferation in XAV-939 treated tumor cells, suggesting that CUEDC2 inhibits tumor cell growth through Wnt/β-catenin signaling." (PMID 36231027, 2022). "Therefore, the inhibitory effect of CUEDC2 on NF-κB and JAK1/STAT3 is likely to prevent tumorigenesis, rather than promoting tumor growth." (PMID 26023733, 2015).
cancer (7 papers, 2015 to 2022). A tumor composed of atypical neoplastic, often pleomorphic cells that invade other tissues. "Aberrations in CUEDC2 gene expression have been reported in several human cancers; however, the role of CUEDC2 in the establishment of the hyperactivation of Wnt signaling in TNBC remains to be defined." (PMID 36231027, 2022). "It should be noted that CUEDC2 has multiple functions as an independent driver in different types of cancer." (PMID 36231027, 2022). "CUEDC2 is expressed in different tissues or organs, such as the heart, brain and liver as well as in various cancer types." (PMID 33494071, 2021). "Studies have confirmed that CUEDC2 is involved in inflammatory responses induced by different types of cancers." (PMID 33494071, 2021). "It is interesting to explore the similar molecular mechanisms how CUEDC1 and CUEDC2 inhibit cancer progression, and these mechanisms are worthy of research in the future." (PMID 33099540, 2020). "Further studies are needed to elucidate the molecular mechanisms through which CUEDC2 exerts these disparate effects in different cancers." (PMID 26023733, 2015). "The similar molecular mechanism how CUEDC1 and CUEDC2 inhibit cancer progression might be they both could inactivate the canonical IκB kinase (IKK)-dependent NF-κB signaling pathway." (PMID 33099540, 2020). "As a multifunctional protein, the function of CUEDC2 in cancers is debated." (PMID 32978519, 2020). "However, the inhibitory role of CUEDC2 in NF-κB activation seems contradictory to its cancer-promoting function as a cell cycle regulator during tumorigenesis." (PMID 29991678, 2018). "However, it needs to be emphasized that the function of CUEDC2 appears to be different in different types of cancers." (PMID 26023733, 2015). "Importantly, the function of CUEDC2 appears to be different in different types of cancers." (PMID 33099540, 2020). "We have previously reported that CUE domain containing 2 (CUEDC2) not only promotes the ubiquitination and degradation of the progesterone receptor but also plays indispensable roles in inflammation and cancer." (PMID 27286733, 2016).
cardiovascular diseases (1 paper, 2016). "Therefore, we tested the protein level of CUEDC2 in the heart upon acute I/R injury or chronic overload stress, which were the most common pathophysiological stress in cardiovascular diseases." (PMID 27286733, 2016).
infection (1 paper, 2020). The state of being infected such as from the introduction of a foreign agent such as serum, vaccine, antigenic substance or organism. "In addition, the overexpression of Cuecd2 using Ad-CUEDC2 infection significantly inhibited BMP2-induced ALP activity and mineralized nodule formation." (PMID 32393737, 2020).
CUEDC2 also shares sentences with these, for which no sentence is quoted: Cerebral ischemia (2 papers); acute myeloid leukaemia (1); acute myocardial infarction (1); myocardial ischemia (1); ovarian serous carcinoma (1); Sepsis (1); skin cancer (1).